JAK2 (Janus kinase 2)
Diseases named in the same sentence as JAK2 in open-access papers (continued):
Sharing a sentence is not in itself a finding about the gene and the disease.
Thrombocytosis (continued). "We investigated five patients with previous history of MPN, which four had initial diagnosis of ET (one case harboring JAK2 p.Val617Phe and the remaining three CALR type II p.Lys385fs*47), and one was diagnosed with MPN/myelodysplastic syndrome with thrombocytosis (SF3B1 p.Lys700Glu)." (PMID 29515972, 2018). "In addition to thrombocytosis, our Jak2V617F/+ mice did develop erythrocytosis, which persisted in the absence of c-Mpl; this is likely to depend on activation of the EPO-R by mutant JAK2 as previously suggested." (PMID 38491305, 2024). "In CML patients, the persistence or occurrence of thrombocytosis, despite WBC decrease and good molecular BCR::ABL1 response under TKI, should alert clinicians to perform molecular screening for Ph-negative MPN, including JAK2, MPL, and CALR mutations." (PMID 38596359, 2024). "In addition, several dozen alternative somatic or germline “noncanonical” mutations of JAK2 were found in rare MPN, MPN-like or hereditary polyglobulia or thrombocytosis cases." (PMID 37639050, 2023). "No studies have reported a paradoxical thrombocytosis in response to JAK2 inhibition to date." (PMID 24086539, 2013).
rheumatoid arthritis (93 papers, 2011 to 2026). A chronic, systemic autoimmune disorder characterized by inflammation in the synovial membranes and articular surfaces. "Baricitinib is an oral synthetic inhibitor of the Janus-associated tyrosine kinases JAK1 and JAK2 used in the management of rheumatoid arthritis (RA)." (PMID 34873553, 2021). "Tofacitinib, which primarily inhibits JAK1 and JAK3 with partial JAK2 inhibition, is approved for conditions like rheumatoid arthritis (RA) and ulcerative colitis (UC), but has emerging applications in dermatologic diseases." (PMID 41235382, 2025). "Mechanistic studies have indicated that P. scandens suppresses Janus kinase 2–signal transducer and activator of transcription 3 phosphorylation, suggesting its therapeutic potential for rheumatoid arthritis via inflammatory pathway inhibition." (PMID 40852586, 2025). "This study assessed the potential impact of tofacitinib and baricitinib, two JAK inhibitors with different JAK2 inhibition profiles, on type 2 diabetic patients with rheumatoid arthritis." (PMID 38541086, 2024). "Through the present study, we aim to assess the potential impact of tofacitinib and baricitinib, two JAK inhibitors with different JAK2 inhibition profiles, on type 2 diabetic patients with rheumatoid arthritis." (PMID 38541086, 2024). "The main strength of our study lies in being the first that, in real-world clinical practice, aimed to elucidate the transcendence of JAK2 inhibition in type 2 diabetic patients with rheumatoid arthritis." (PMID 38541086, 2024). "Filgotinib, a JAK1/JAK2 inhibitor, has been administered to patients with rheumatoid arthritis (RA) since 2016." (PMID 39684719, 2024). "Baricitinib is a JAK1 and JAK2 inhibitor approved for treating active rheumatoid arthritis and atopic dermatitis." (PMID 39525758, 2024). "In another study, baricitinib, an inhibitor with selectivity for JAK1/JAK2, currently approved for the treatment of rheumatoid arthritis, was seen to allow treated patients to significantly reduce steroid use." (PMID 38334659, 2024). "Baricitinib is an oral, specific, and reversible JAK1 and JAK2 inhibitor authorized for the management of rheumatoid arthritis, atopic dermatitis, and severe alopecia areata in many countries." (PMID 39525758, 2024). "The interferon (IFN)-γ/pSTAT1 pathway, related to the impairment of pancreatic β-cells in type 2 diabetes mellitus and involved in the pathogenesis of rheumatoid arthritis, is primarily mediated by JAK2." (PMID 38541086, 2024). "Baricitinib is a JAK1/JAK2 inhibitor approved for rheumatoid arthritis, atopic dermatitis, alopecia areata, and juvenile idiopathic arthritis." (PMID 38731900, 2024). "Baricitinib is an oral selective inhibitor of JAK1 and JAK2, which has demonstrated significant efficacy in rheumatoid arthritis (RA) patients." (PMID 39430463, 2024). "Baricitinib is a JAK1/JAK2 inhibitor used to treat severe rheumatoid arthritis, alopecia areata, and AD." (PMID 39076971, 2024). "Baricitinib, a selective JAK1 and JAK2 inhibitor, has been approved for treatment of active rheumatoid arthritis and reported in treatment of some other autoimmune diseases including systemic lupus erythematosus." (PMID 36793118, 2023). "EU-Idd exerts anti-inflammatory and osteoprotective effects by regulating the JAK2/STAT3 pathway in rheumatoid arthritis." (PMID 37123081, 2023). "As a target of miR-218-5p, KLF9 controlled the autophagy, apoptosis, and oxidative stress by regulating the JAK2/STAT3 signaling pathway in rheumatoid arthritis synovial fibroblasts." (PMID 36846202, 2023). "Baricitinib is a tyrosine-protein kinase JAK2 inhibitor mainly used for rheumatoid arthritis, and among its pharmacological properties it has an antiviral effect on the entry of a virus." (PMID 35422702, 2022).
rheumatoid arthritis (continued). "Baricitinib, a Janus kinase (JAK) JAK1/JAK2 inhibitor used to treat rheumatoid arthritis, has been proposed to prevent intracellular uptake of SARS-CoV-2 by targeting the angiotensin-converting enzyme 2 (ACE2) receptor, suppressing cytokine storm." (PMID 35106192, 2021). "Baricitinib is a small-molecule Janus kinase 1 (JAK1) e 2 (JAK2)” inhibitor that is currently approved for treatment of rheumatoid arthritis." (PMID 34072708, 2021). "Baricitinib, a selective inhibitor for janus kinase (JAK) 1 and JAK2, is approved for use in rheumatoid arthritis." (PMID 34497607, 2021). "One of the new drugs that are in clinical development for IBD, but already approved for the treatment of rheumatoid arthritis, is Baricitinib, a selective Janus kinase (JAK1, JAK2) and AP2-associated protein kinase 1 (AAK1) inhibitor." (PMID 32714386, 2020). "Cell and animal models and phase II studies have shown potent, pre- and clinical efficacy of itacitinib against psoriasis and rheumatoid arthritis in a JAK2-independent manner." (PMID 32397643, 2020). "Of the four subtypes of the JAK family (JAK1, JAK2, JAK3, and TYK2), JAK1 is involved in signaling through inflammatory cytokines such as IL-6, and it is known to cause lymphocyte activation and proliferation in rheumatoid arthritis (RA)." (PMID 39944226, 2025). "It is proposed that the ability of YSTB to slow the progression of rheumatoid arthritis may be related to modulating the JAK/STAT pathway by degrading the phosphorylated expression of JAK2, JAK3, and STAT3 proteins, whereas elevated SOCS3 protein expression." (PMID 38966637, 2024). "Tofacitinib, which inhibits JAK1, JAK3, and to a slightly lesser extent JAK2, therefore may function to reduce or inhibit inflammatory pathways that lead to rheumatoid nodule formation." (PMID 39070924, 2024). "Therapeutically, the Janus kinase (Jak) 1/Jak2 inhibitor baricitinib reduces the pathology of rheumatoid arthritis and may also reduce pain." (PMID 39596013, 2024). "Furthermore, JAK2/STAT3 activation has been reported to mediate testicular impairment and sperm aberrations in rheumatoid arthritis-associated testicular damage." (PMID 39065759, 2024). "Hence, Jak1 and Jak2 represent novel therapeutic targets for osteoporosis as well as inflammatory bone diseases including rheumatoid arthritis." (PMID 28708884, 2017). "Baricitinib (Olumiant), a small molecule JAK1/JAK2 inhibitor, is approved for the treatment of rheumatoid arthritis (RA) and has been proven to reduce lung fibrosis and inflammation in patients with RA-associated ILD (RA-ILD)." (PMID 35626663, 2022). "Baricitinib is an oral synthetic Janus Kinase inhibitor that inhibits JAK1 and JAK2, and the new kid on the block in the treatment of rheumatoid arthritis (RA)." (PMID 34873553, 2021). "Baricitinib, an oral-administrated selective inhibitor of the JAK1 and JAK2, is recently approved for rheumatoid arthritis (RA) treatment." (PMID 30777075, 2019). "In July 2021, the FDA issued the Emergency Use Authorization (EUA) for Eli Lilly's Janus kinase 1 and Janus kinase 2 (JAK1 and JAK2) inhibitor baricitinib (Olumiant®) as monotherapy, which is already approved for severe rheumatoid arthritis." (PMID 40371758, 2025). "Recent studies have shown that hsa-miR-218-5p regulates the proliferation, apoptosis, autophagy and oxidative stress of rheumatoid arthritis synovial fibroblasts by targeting Kruppel like factor 9 (KLF9) and activating JAK2/STAT3 signaling pathway." (PMID 37525657, 2023). "Tofacitinib is used against rheumatoid arthritis and other inflammatory diseases and mainly targets JAK1 and JAK3, with a lesser effect on JAK2." (PMID 36979068, 2023). "Upadacitinib, an oral reversible JAK inhibitor with greater inhibitory potency for JAK1 than JAK2, JAK3, and TYK2, has been approved by the U.S. FDA for treating AD, rheumatoid arthritis, and psoriatic arthritis." (PMID 36569854, 2022).
rheumatoid arthritis (continued). "Baricitinib is a Janus kinase (JAK) inhibitor used to treat refractory rheumatoid arthritis and blocks the subtypes JAK1 and JAK2." (PMID 35096866, 2022). "Tofacitinib, an effective oral JAK2/1/3 inhibitor, and baricitinib, a selective JAK1/JAK2 inhibitor, were approved by the FDA for the treatment of rheumatoid arthritis (RA) and ulcerative colitis(UC)." (PMID 34335579, 2021). "We recently reported that A77 1726, the active metabolite of the anti-rheumatoid arthritis drug leflunomide, is able to inhibit the replication of influenza A virus and porcine epidemic diarrhea virus by targeting JAK1 and JAK2." (PMID 33050000, 2020). "Taking advantage of the inhibition of the cytokine cascade of JAK2 inhibitors, these compounds are going to be used not only to treat patients with hematological neoplasms but may also be beneficial to treat patients with rheumatoid arthritis or other inflammatory diseases." (PMID 22400031, 2012). "Taking advantage of the inhibition of the cytokine cascade of JAK2 inhibitors, these compounds are going to be used not only to treat patients with MPN, but also patients with autoimmune diseases as rheumatoid arthritis, Crohn's disease, or Colitis ulcerosa." (PMID 22400031, 2012). "Although the goal was 100-fold selectivity for JAK3 over JAK2, the compound ultimately inhibited JAK1 and JAK2 as well, which turned out to be beneficial for broader anti-inflammatory effects, particularly in diseases like rheumatoid arthritis and IBD." (PMID 40869955, 2025). "For example, it was shown to effectively inhibit Receptor activator of nuclear factor-κB ligand (RANKL) expression by inhibiting the JAK2/STAT3 pathway and upregulating SOCS3 in rheumatoid arthritis fibroblast-like synoviocytes (FLS) stimulated with IL-6/sIL-6R." (PMID 39769302, 2024). "Tofacitinib citrate is approved for medical use “to treat adults with moderately to severely active rheumatoid arthritis who have had an inadequate response to or are intolerant of methotrexate”.395–399 Baricitinib, sold under Oluminant, acts as a JAK1 and JAK2 inhibitor." (PMID 36797236, 2023). "Theophylline is an anti-inflammatory substance, and previous studies have shown that theophylline can reduce the levels of IL-6, COMP, JAK2, STAT3, RANKL, iNOS, and eNOS by modulating the JAK/STAT/RANKL signaling pathway, thereby alleviating the inflammatory response in rheumatoid arthritis." (PMID 37076836, 2023). "One limitation is that we have not yet explored the optimal therapeutic dose of EU-Idd for rheumatoid arthritis, and another limitation is that our results have not been verified by using JAK2/STAT3 pathway inhibitor." (PMID 37123081, 2023). "Baricitinib was approved by the U.S. FDA as a selective JAK1 and JAK2 inhibitor for the indications of rheumatoid arthritis and Coronavirus Disease 2019 (COVID-19) but not yet for atopic dermatitis." (PMID 36569854, 2022). "Research demonstrates that angiogenesis can be hampered under an environment of inflammation as well as impede the inflammation-induced expression of VEGF in MH7A cell partly through the pathway IL-6/JAK2/STAT3/VEGF, providing new prospects for treating rheumatoid arthritis." (PMID 33499333, 2021). "Using KO simulations, we identified NFkB, JAK1/JAK2, and ERK1/Notch1 as potential targets that could selectively suppress proinflammatory macrophages and GSK3B as a promising target that could promote anti-inflammatory macrophages in rheumatoid arthritis." (PMID 38272919, 2024). "It is an oral inhibitor of the enzymes JAK1, JAK2, and JAK3, which was approved in 2012 for the treatment of moderate to severe rheumatoid arthritis (RA)." (PMID 39770590, 2024). "On the other hand, Tofacitinib inhibits JAK1, JAK2, JAK3 and is approved by the Food and Drug Administration (FDA) for treating rheumatoid arthritis (RA), psoriatic arthritis and ulcerative colitis." (PMID 38920670, 2024).
rheumatoid arthritis (continued). "The co-activation of NF-κB and JAK2/STAT3 induce a massive and sustained production of proinflammatory cytokines, such as IL-6 and IFN-γ, which are critical for the development of inflammatory diseases including rheumatoid arthritis (RA) and multiple sclerosis (MS)." (PMID 35246140, 2022). "The baseline risk of HZ in rheumatoid arthritis is 1.5–2-fold higher compared to the general population, and the incidence of HZ reported with tofacitinib, which preferentially inhibits JAK1, JAK2, and JAK3, is double that reported in RA." (PMID 32974356, 2020). "In the present article, we describe the preclinical evaluation of a potent, orally active, small-molecule inhibitor of Janus kinase 2 (JAK2), CEP-33779, for the treatment of rheumatoid arthritis (RA)." (PMID 21510883, 2011). "The JAK2 inhibitor baricitinib (Olumiant, from Eli Lilly) was FDA-approved in June 2018 for the treatment of moderately to severely active rheumatoid arthritis (RA)." (PMID 33240910, 2020). "Growing evidence supports that downregulation of JAK2 and STAT3 phosphorylation can mitigate inflammation, as seen in conditions such as cerebral ischemic stroke (IS) injury, LPS-induced microglial cell inflammation, atopic dermatitis, and rheumatoid arthritis (RA)." (PMID 39187810, 2024). "The expression of RANKL, JAK2, STAT3, and SOCS3 proteins was assessed by western blot analysis, real-time PCR and ELISA in IL-6 combined with soluble IL-6 receptor (sIL-6R)-stimulated rheumatoid arthritis (RA)-FLS with or without tacrolimus treatment." (PMID 23406906, 2013).
ovarian carcinoma (92 papers, 2002 to 2026). A malignant neoplasm originating from the surface ovarian epithelium. "In another study, PIK3R1 copy number loss or reduced PIK3R1 expression rendered ovarian cancer cells vulnerable to the inhibition of AKT or JAK2/STAT3 inhibitors." (PMID 39858051, 2025). "PIK3R1 loss renders ovarian cancer cells vulnerable to inhibition of AKT or JAK2/STAT3." (PMID 30755611, 2019). "In addition, we report that the JAK2/STAT3 pathway is required to sustain EGF-induced EMT-associated phenotypes in ovarian cancer cells, indicating that in EGF-driven ovarian tumours JAK2/STAT3 signalling may be critical in regulating metastasis." (PMID 19088723, 2009). "As a vital immunoregulatory cytokine, IL‐6 mediates chemoresistance through various signaling pathways, with the JAK2/STAT3 signaling pathway being particularly prominent in ovarian cancer." (PMID 40968783, 2026). "In ovarian cancer tissues and cell lines, miR-217 is downregulated, which leads to increased IL-6 secretion and the activation of the JAK2/STAT3 signaling pathway, driving M2-like macrophage polarization." (PMID 40330466, 2025). "For instance, one study demonstrated that LCP1 contributes to olaparib resistance by activating the JAK2/STAT3 signaling pathway in ovarian cancer." (PMID 40740857, 2025). "We reported that abnormal expression of LCP1 led to ovarian cancer cell resistance to olaparib by activating the JAK2/STAT3 signaling pathway and EMT." (PMID 39588922, 2024). "In summary, in this study, we demonstrated that LCP1 is involved in olaparib resistance in ovarian cancer cells by activating the JAK2/STAT3 pathway and EMT." (PMID 39588922, 2024). "We demonstrated that LCP1 can promote EMT by activating the JAK2/STAT3 signaling pathway in ovarian cancer cells, thereby promoting tumor cell metastasis and invasion." (PMID 39588922, 2024). "The LCP1/JAK2/STAT3 axis is a key signaling pathway involved in olaparib resistance in ovarian cancer." (PMID 39588922, 2024). "The study showed that leptin stimulation led to an increased proliferation, survival and migration of LEPR-expressing ovarian cancer cell lines, with these effects shown to be mediated by the JAK2/ STAT3 pathway." (PMID 37238197, 2023). "CHAF1A promotes the proliferation and growth of epithelial ovarian cancer cells and inhibits the apoptosis of cancer cells by activating JAK2/STAT3 signaling pathway, which is expected to be a new target for the treatment of epithelial ovarian cancer." (PMID 37575547, 2023). "The “erasers” ALKBH5 and HOXA10 form a positive feedback loop, which eliminates the m6A modification of JAK2 mRNA and promotes cisplatin resistance in epithelial ovarian cancer by activating the JAK2/STAT3 signaling pathway." (PMID 37264402, 2023). "In conclusion, CHAF1A promotes the proliferation and growth of epithelial ovarian cancer cells by affecting the phosphorylation of JAK2/STAT3 signaling pathway." (PMID 37575547, 2023). "On analyzing human ovarian cancer specimens, JAK2 and STIP1 expression levels were found to be positively correlated with each other." (PMID 35269562, 2022). "RHPN2, a RhoA-binding protein, promotes malignant cell proliferation in ovarian cancer by activating the JAK2/STAT3 signaling pathway." (PMID 35893033, 2022). "We have previously shown that STIP1 maintains JAK2 protein stability and prevents apoptosis in ovarian cancer." (PMID 35269562, 2022). "Tumor growth and resistance to cisplatin were promoted via ALKBH5-HOXA10 loop through mediating JAK2/STAT3 signaling pathway in epithelial ovarian cancer." (PMID 36545327, 2022). "Cisplatin resistance in ovarian cancer cells has been associated with an increased phospho-STAT3 expression; conversely, both JAK2 and STAT3 inhibitors can enhance cisplatin sensitivity." (PMID 35269562, 2022). "ALKBH5 activates the JAK2/STAT3 signaling pathway by mediating JAK2 m6A demethylation to promote cisplatin resistance in ovarian cancer." (PMID 35945641, 2022).